CXCR3 (C-X-C motif chemokine receptor 3)
Diseases named in the same sentence as CXCR3 in open-access papers (continued):
Sharing a sentence is not in itself a finding about the gene and the disease.
infection (continued). "Accordingly, mice were orally inoculated with cysts, and relative levels of CXCR3, CXCL9 and CXCL10 mRNA expression were measured over the course of acute infection." (PMID 24130498, 2013). "We find that CD4+ T lymphocytes, recruited in dependence upon their expression of the chemokine receptor CXCR3, mediate activation of intestinal mucosa inflammatory monocytes via secretion of IFN-γ, in turn resulting in control of infection." (PMID 24130498, 2013). "Prominent ASC expansion in cervical lymph nodes prior to CNS migration during MHV-JHM infection is accompanied by their expression of CXCR4 and CXCR3." (PMID 23435240, 2013). "We found a large increase in CXCR3 populations of both CD4+ and CD8+ T lymphocytes in MLN, spleen (SPL) and LP compartments following infection." (PMID 24130498, 2013). "CXCR3-mediated accumulation of ASC is consistent with the sustained expression of the CXCR3 ligands CXCL9, CXCL10, and CXCL11 throughout CNS MHV-JHM infection." (PMID 23435240, 2013). "Our data show that CXCR3 enables Th1 recruitment to the intestinal LP, where these cells instruct activation of CCR2-dependent inflammatory monocytes, in turn controlling infection." (PMID 24130498, 2013). "The chemokine receptors involved in NK cell migration to the site of infection have been assessed for a few pathogens, and from these studies it appeared that CCR2, CCR5, CXCR3 and CX3CR1 play a key role in NK cells migration during infection." (PMID 23272202, 2012). "These factors interact with CXCR3 displayed on memory and activated T cells, especially IFN-γ-producing T cells, and promote cell chemotaxis to infection site." (PMID 22815692, 2012). "For instance, CD127hi cells also express high levels of CD27, which is a member of tumor necrosis factor receptor (TNF-R) family and the chemokine receptor, CXCR3, but these cells are found to have low expression of CD43 after infection with the Sendai virus." (PMID 23346085, 2012). "Among Tc17 cells that were recruited to the lungs of vaccinated mice after infection, the expression of CCR6 (84%) was much higher than that of CXCR3 (49%)." (PMID 22829762, 2012). "CXCR3 is expressed on the surface of Th1 cells as well as NK and NKT cells and regulates the migration of these cells to sites of infection." (PMID 22189154, 2011). "The observed up-regulation of CXCR3 and CCR5 on NK cells in both the bone marrow and the spleen after infection, suggests that these receptors contribute to the recruitment of NK cells to the spleen during L. monocytogenes infection." (PMID 21179539, 2010). "CXCL-10 initiates its biological functions through binding to its high affinity receptor CXCR-3 leading to recruitment of the activated effector lymphocytes including CD4+ and CD8+ T cells as well as NK cells to the site of infection or injury." (PMID 19442267, 2009). "This analysis revealed similar numbers of WT NK cells in non-white pulp regions before and after infection, while Cxcr3 KO NK cells were enriched in non-white pulp regions only after infection." (PMID 40694683, 2025). "The CXCR3+ P2 BSM population expressed low levels of Tbet, which may reflect prior IFN-g exposure during infection, and were distinct from atMBCs which expressed high levels of Tbet." (PMID 40964019, 2025). "Compared with adults, children had higher frequencies of spike- and non-spike–specific CXCR3+CCR6–CD4+ T cells (CXCR3+) during the acute phase of infection (spike: P = 0.008, non-spike: P < 0.0001)." (PMID 40906527, 2025). "This study aimed to investigate chemokine patterns and their significance on CXCR3 expression and chemotaxis in the livers of patients with CHD and CHB and in relevant in vitro and in vivo infection models, such as primary human hepatocytes (PHHs) and human liver chimeric mice." (PMID 39980752, 2025).
infection (continued). "Further studies are necessary to determine whether both CXCR3− and CXCR3+ cTfh arise from the same Tfh population, if correlations between total cTfh and Tfh populations exist later in infection, and if these observations are specific to AHI." (PMID 39932316, 2025). "For instance, in the salivary glands, sites of cytomegalovirus infection and replication, CXCR3-mediated CD8+ T cell migration appears to be an intrinsic property of the tissue rather than a response to infection." (PMID 41479900, 2025). "The evasion of fungal immune control mechanisms with down-regulated Th1 (IFN-γ, TNF-α, and IL-2) and Th17 T cell cytokines (IL-17A) and CXCR3+ T cell chemoattractant chemokine (CXCL10) responses, allows more vigorous replication of Cryptococcus and overwhelming infection." (PMID 39928682, 2025). "Notably, CTLA-4 expression was also increased in CD4+ CCR4+ CXCR3− TH2 and CD4+ CCCR6+ CCR4− CXCR3− TH9 at 8-weeks and 12-weeks post-infection, respectively." (PMID 39411786, 2024). "In naive cells, the expression levels of CCR10, CXCR3, and CCR6 were similar during infection." (PMID 39867906, 2024). "However, during infant infection, this difference was lost, and the expressions of CCR6, CCR5, and CXCR3 were found to be equivalent." (PMID 39867906, 2024). "Thus, a substantive fraction of memory CD8 T cells in circulation or in various tissues express CXCR3 and/or CX3CR1 and, hence, are poised to rapidly traffic into infected tissues such as lungs, upon infection." (PMID 37796612, 2023). "Such treatment markedly increased CXCR3 expression in both memory and naïve CD8 T cells, enhancing the migration of both antigen-specific and bystander CD8 T cells into inflamed lungs after infection." (PMID 38037190, 2023). "In contrast, following infection with JKD6159-gD, activated CD4+ T cells were predominantly IL-17 producing Th17, and of the divided cells, 40% downregulated CD62L, 26% upregulated CCR6, while only 20% upregulated CXCR3." (PMID 35637249, 2022). "Infection with HSV-1 resulted in the generation of predominately IFNγ producing Th1 cells, and assessment of the divided cells (CFSElo) revealed that 78% downregulated CD62L, 5% upregulated CCR6, while 70% upregulated CXCR3." (PMID 35637249, 2022). "Moreover, EBV+ CD19+/CXCR3+/CD11c+/FCRL4+ cells and parental CD19+ populations proliferated to a similar extent in response to infection." (PMID 36248899, 2022). "Most CD4+ T-cells in the blood, spleen, and MLN of control HIS-NSG mice expressed CC-chemokine receptor 4 (CCR4) without the presence of CCR5 and CXC-chemokine receptor 3 (CXCR3), which were indeed upregulated upon infection." (PMID 34685494, 2021). "Nevertheless, although IL-17A did neither affect the early expression of CXCR3 chemokines nor vaccine-induced protection in the early phase of infection with Mtb, the induction of antigen-specific Th1 cells after vaccination appeared to be dependent on IL-17A." (PMID 34351501, 2021). "Further, predictive modeling indicated a significant interaction between CXCR3+ and AM3K+ (macrophages) cells, suggesting that progression to clinical disease state aligns with increased numbers of these cell types at the site of infection." (PMID 33849661, 2021). "Our results showed that body weight recovery slowed down in the absence of CXCR3 during the sub-acute to chronic infection period." (PMID 34835465, 2021). "SjS patients with past infection or recent infection/reactivation showed increased CXCR3+Th1 and CXCR3+Tfh1 cells compared to those without active infection." (PMID 33603079, 2021). "However, the CXCR3+population in both PBMCs and CD8+ cells in old RMs increased rapidly compared with that in young RMs after infection, while changes in the T-bet+ population showed the opposite result." (PMID 34471088, 2021).
infection (continued). "The CXCR3 and AM3K interaction model to predict subclinical disease state has the ability to predict subclinical disease earlier during this stage of infection, allowing earlier interventions to mitigate maintenance and spread of infection." (PMID 33849661, 2021). "A significant increase in Ki67 and CXCR3 expression by NK cells was evident, but CCR2 and CCR5 levels remained unchanged, suggesting that NK cell infiltration and proliferation occurred after znBAZ infection." (PMID 34305935, 2021). "The data also showed that MAIT cells expressed more CD69 (gut aGVHD vs. no-event, p = 0.02; gut aGVHD vs. infection or fever, p = 0.011), CXCR3, and CXCR4 in the gut aGVHD group than in the other two groups." (PMID 34539656, 2021). "From these data, we can conclude that CXCR3 anti-ZIKV activity is not due to changes in cellular viability during infection or IP-10 stimulation." (PMID 33378361, 2020). "Also, we demonstrated that CXCR3 is essential to specific CD8+ T cell migration into infected hearts and infection control during immunization with ASP-2-based anti-T." (PMID 32574175, 2020). "In rectal tissue, the high proportion of CCR6+CXCR3+ T cells coexpressing the CCR5 HIV coreceptor may allow preferential productive infection of this subset." (PMID 31796951, 2020). "Furthermore, we demonstrated that specific ligands for both CCR6 and CXCR3 (MIP‐3α and CXCL9/10, respectively) were expressed in the trachea after infection, suggesting their involvement in the recruitment of γδ T cells." (PMID 31777067, 2020). "Conversely, Thapa and colleagues have shown that CXCR3 is important to the T lymphocytes proliferation, however, CXCR3 was important to T cell proliferation in early days of infection by HSV-2 virus and here we evaluated the proliferation on day 15 after infection." (PMID 32574175, 2020). "To probe apoptosis induction, we measured activation of caspases 3 and 7 at 24 hours-post infection, with and without IP-10, CXCR3 agonist, or CXCR3 antagonist pre-treatment." (PMID 33378361, 2020). "PrimePCR array analysis of hNS/PCs showed that the mRNA levels of inflammatory cytokine related genes (IL-1A, TNFα, IL28A, IL29, NF-KB2), chemokines (CSF2, CCL3, CCL4, CXCR3),TLRs (TLR3, TLR8), IL-10, and Casp9 were all reduced in the Smaducin-6 treated group following ZIKV-FSS13025 infection." (PMID 32544190, 2020). "CXCR3 and its ligands, the IFN-γ-inducible C-X-C chemokines CXCL9, CXCL10, and CXCL11, are important for migration of activated CD4+ Th1 cells to inflamed tissues and sites of infection." (PMID 30915078, 2019). "Although specific CD8+ T cells infected expressed higher levels of CXCR3 on cell surface, CD8+ T-cells from the immunized group had a higher migration index compared to specific CD8+ T cells generated only by infection, after the ex vivo stimulation with CXCL9 and CXCL10, but not with CXCL11." (PMID 31356587, 2019). "CXCR3 is a chemokine receptor that is highly expressed on effector CD4+ and CD8+ T cells and grants them entry into otherwise restricted sites of Th1-type inflammation and infection." (PMID 29515587, 2018). "Treatment with HIV gp120 before DPG-3 infection and co-culture led to a significant increase in IFNγR expression, but not CXCR3 expression." (PMID 28198424, 2017). "In our study, we also show that CXCR3 regulates CD8 and CD8+TNF-a+ cell migration after infection." (PMID 29552679, 2017). "Moreover, due to their apparent roles in infection, inflammation, angiogenesis, and cancer, thoroughly understanding the IFN-related CXCR3 chemokine system would be of clinical value, both from a diagnostic and therapeutic point of view." (PMID 29379506, 2017). "Multifunctional Th17 cells (IFN-γ+IL-17A+) co-expressing CXCR3/CCR6 are known to upregulate the ligands for CXCR3 (CXCL9/CXCL10/CXCL11) on the lung parenchymal cells, which helps to recruit Th1 cells to the site of infection." (PMID 28985739, 2017).
infection (continued). "The absence of CXCR3 promotes bacterial propagation and dissemination, significantly compromising host resistance to infection." (PMID 28860493, 2017). "As CXCR3+ CD4+ T-cells are the main cellular targets of HIV, it is conceivable that IP-10 enhances the trafficking of HIV target cells to lymphoid tissues, thereby promoting new rounds of infection and helping to establish viral reservoirs." (PMID 27509048, 2016). "CXCR3 and its ligands, CXCL9, CXCL10, and CXCL11, play a pivotal role in the regulation of inflammatory and infectious diseases, in which CXCR3-bearing effector leukocytes are recruited to the sites of inflammation or infection." (PMID 27068264, 2016). "Furthermore, CXCR3, whose signal brings newly activated CD8 T cells to sites of ongoing infection, was also decreased in DKO OT1 T cells." (PMID 27014906, 2016). "Similar attenuation of macrophage attraction to local infections could be achieved by treatment with NBI74330, a high-affinity antagonist of CXCR3." (PMID 25573892, 2015). "Therefore, the expression of CXCR3 on splenic CD4+ and CD8+ T cells was examined on day 7 post-infection to determine if iron supplementation was attenuating T cell chemotaxis." (PMID 25768944, 2015). "Interestingly, on day 3 post-infection, a greater percentage of splenic CD4+ T cells in the FeD mice had an activated phenotype and expressed CXCR3." (PMID 25768944, 2015). "Moreover there is a group of molecules, including LTA, LTB, IL21, IFNAR2, CXCR3, IL17F and CD40LG, whose expression increased over the course of USA300 infection." (PMID 25719526, 2015). "In the absence of CXCR3, we found that lamina propria neutrophil levels were increased during infection, as was their activation status as measured by TNF-α expression." (PMID 24130498, 2013). "Strikingly, adoptive transfer of wild-type but not Ifnγ−/− CD4+ T lymphocytes into Cxcr3−/− animals prior to infection corrected the defect in inflammatory macrophage activation, simultaneously reversing the susceptibility phenotype of the knockout animals." (PMID 24130498, 2013). "This damage was infection-dependent as intestines from non-infected WT and Cxcr3−/− mice both had normal architecture with few inflammatory cells." (PMID 24130498, 2013). "In these studies, it was also clear that the absence of CXCR3/CCR5 restricted the accumulation of effector T cells to sites of infection/inflammation as plenty of cells were recruited to the lung, but not to areas of viral replication within the infected lung." (PMID 23346085, 2012). "In untreated rabbits, most of these genes were progressively induced by Mtb infection from 4 to 8 weeks, and many had reached a plateau (IFN-γ, IL13, IL6, MIF, CCL4, NFκB, APRIL, TLR2, RAB7 and LAMP2) or were even reduced (IL10, CXCR3, GMCSF and PI3K3) by 12 weeks post-infection." (PMID 21949656, 2011). "In this study, both IP-10 and CXCR3 were elevated in the NK cells of ATB patients, suggesting that in ATB patients, NK cells exhibit a heightened response to chemotactic signals, with increased expression of surface receptors that facilitate their migration to the site of infection." (PMID 40589756, 2025). "Thus, CXCR3 and its ligands could play an important part in the regulation of Tc1 CD8+ T cell migration to the site of infection." (PMID 37761328, 2023). "Cluster 27, activated emTc, showed higher expression of CXCR3 (fold change GSD1b/control = 1.78, p-value = 0.01), which is considered to represent an activation marker for CD8+ T cells; for this effector memory T cell population, it likely indicates activation and targeting to sites of infection." (PMID 36865166, 2023). "These individuals had reduced numbers of circulating T follicular helper cells and an enriched population of CXCR3+CD127+CD8+ T cells after two doses of SARS-CoV-2 vaccination, which may compensate for sub-optimal serological responses in the event of infection." (PMID 36380764, 2022).
infection (continued). "Evaluation of infection-induced changes in CD4 T-cell differentiation at Day 7 revealed a strong phenotypic shift to Th1 effectors (CXCR3+), Th1 polarized Tfh cells (CXCR3+ CXCR5+) and Th1 Th17 (CXCR3+ CCR6+) CD4 T cells as demonstrated by tSNE plots constructed using flow data." (PMID 33483492, 2021). "However, CD4+ T cells primed and differentiated in an IL-10–enriched environment displayed reduced expression of CXCR3 and, because they did not migrate into the lung parenchyma, their ability to control infection was limited." (PMID 34554927, 2021). "However, the body weight difference that we saw during the chronic infection phase suggests that the lack of CXCR3 in the KO mice impaired their recovery from the damage inflicted by the acute infection." (PMID 34835465, 2021). "The CXCL9, CXCL10, CXCL11/CXCR3 axis and TNFSF13B play a role in both these recruitment and activation processes, responsible for attracting Th1 cells, cytotoxic lymphocytes and natural killer cells to the site of the infection, and related to B-cell activation, respectively." (PMID 34276658, 2021). "As CXCR3 is a known target of T-bet, and is important for CD4+ T cell trafficking to sites of inflammation, this provides insight into a potential mechanism behind the reduced frequency and numbers of T cells found at, and adjacent to, the site of infection we found in our studies." (PMID 33373420, 2020). "Still, we surmised that the infection-experienced Treg pool may be enriched for memory Tregs of enhanced suppressive capacity that may not be marked by enhanced expression of CXCR3 and thus not be readily detectable within the total Treg population." (PMID 32433493, 2020). "WT as well as CXCR3−/− mice were immune to challenge infection (data not shown)." (PMID 30915078, 2019). "In addition to enhanced CXCR3 expression, we evaluated the concentrations of the CXCR3 ligands IP-10/CXCL10 and MIG/CXCL9 in the serum of mice at days 0, 6, 8, 10, 12, and 14 after infection." (PMID 31356587, 2019). "Thus, we assessed the expression of CD127 and CXCR3 on PBMCs following infection with PyV, mCMV, and HV68 to determine whether these viruses give rise to CD127+CXCR3+ cells with potent recall responses that may be alloreactive and mediate CoBRR." (PMID 29963060, 2018). "To determine whether the infection-dependent macrophage recruitment can also be modulated pharmacologically, we tested a chemical inhibitor of human CXCR3, NBI74330, which binds with high affinity to a pocket formed by the transmembrane domains of CXCR3." (PMID 25573892, 2015). "Interestingly CXCR3, an inflammatory chemokine receptor, showed significant increase in the METH treated LCMV infected mice, suggesting that METH modulates the migratory properties of T cells during infection thus affecting immune activation." (PMID 26322025, 2015). "Additionally, attenuation of macrophage recruitment to infection could be mimicked by treatment with NBI74330, a high-affinity antagonist of CXCR3." (PMID 25573892, 2015). "Infection with both low and high virulence isolates resulted in down-regulation of mRNA levels for chemokines CCL2, CCL3L, CXCL2 and chemokine receptors CCR1, CCR5, CXCR3, CXCR4 and up-regulation in expression of mRNAs for CCL4, CXCL10 and chemokine receptor CCR7." (PMID 23265239, 2013). "Interestingly, our previous studies show that not all CXCR3+ NK cells migrate to the site of infection after CLP." (PMID 22992408, 2012). "CXCR3 was also expressed by large numbers (>90%) of NK T cells and a subset of T lymphocytes, but those cell populations did not exhibit trafficking to the site of infection during the initial 8 to 16 hours after CLP." (PMID 22992408, 2012). "The expression of the gut-homing molecules integrin β7, CCR6, and CXCR3 was identified as a “signature” for HIV-specific but not CMV-specific CD4+ T-cells thus providing a new explanation for their enhanced permissiveness to infection in vivo." (PMID 22470433, 2012).